TRAF3 (TNF receptor associated factor 3)
Diseases named in the same sentence as TRAF3 in open-access papers (continued):
Sharing a sentence is not in itself a finding about the gene and the disease.
Stroke (7 papers, 2020 to 2023). Sudden impairment of blood flow to a part of the brain due to occlusion or rupture of an artery to the brain. "Knockdown of circHECTD1 inhibited cell apoptosis and reduced cell damage after stroke through the miR-133b/TRAF3 axis and miR-27a-3p/FSTL1 axis." (PMID 38203348, 2023). "TRAF3 was reported as a promising therapeutic target for stroke management, which covered several neuronal apoptosis signaling cascades." (PMID 33414375, 2021). "The hypomethylation of TNF receptor-associated factor 3 (TRAF3) and of protein phosphatase 1A (PPM1A) is also related to increased stroke occurrence in patients treated with antiplatelet drugs." (PMID 31941075, 2020). "Similarly, hypomethylation of TNF receptor-associated factor 3 (TRAF3), hypermethylation of thrombospondin-1 (THBS1), and increased DNA methyltransferase 3A (DNMT3A) activity are indicated as predictors of stroke outcome." (PMID 36855111, 2023). "Similarly, hypomethylation of TNF receptor-associated factor 3 (TRAF3), hypermethylation of thrombospondin-1 (THBS1), and increased DNMT3A activity are indicated as predictors of stroke outcome, as well degree of ischemic injury." (PMID 36855111, 2023). "Circ_0000647 promotes apoptosis in SK-N-SH cells through the miR-126–5p/TRAF3 axis and may be a new target for stroke treatment." (PMID 38203348, 2023). "Similarly, hypomethylation of TNF receptor-associated factor 3 (TRAF3) and hypermethylation of thrombospondin-1 (THBS1) has also been illustrated to be crucial predictor of stroke-related outcomes." (PMID 36312038, 2022).
Insulin resistance (6 papers, 2016 to 2024). Increased resistance towards insulin, that is, diminished effectiveness of insulin in reducing blood glucose levels. "Thus, it can be concluded that HFD-induced and genetically induced insulin resistance, inflammatory response and hepatic steatosis are negatively regulated by TRAF3 deficiency." (PMID 26882989, 2016). "Taken together, these findings support the notion that elevated Mir802 induces macrophage recruitment and polarization at least partly via downregulation of Traf3, thereby leading to adipose tissue inflammation and insulin resistance." (PMID 39589393, 2024). "In this study, we found that Mir802 promotes adipose tissue inflammation and insulin resistance by targeting TRAF3 in adipocytes." (PMID 39589393, 2024). "TRAF3 expression is significantly increased in the liver of obese mice, and hepatocyte-specific TRAF3 knockout can alleviate insulin resistance." (PMID 35116066, 2022). "Another inspiring study explored that hepatocyte TRAF3 promoted liver steatosis and systemic insulin resistance through targeting TAK1-dependent signaling." (PMID 32579175, 2020). "The essential role of TAK1 in TRAF3-regulated hepatic steatosis and insulin resistance raised another critical question: do TRAF3 and TAK1 directly interact during the progression of this pathological condition?" (PMID 26882989, 2016). "The TAK1-dependent mechanism during TRAF3-regulated insulin resistance, inflammation and hepatic steatosis raises another question: how does TRAF3 regulate TAK1 activation?" (PMID 26882989, 2016). "On the basis of these experiments, we deduced that the proposed interaction between TRAF3 and TAK1 at least partially explain the regulatory function of TRAF3 on hepatic steatosis and insulin resistance." (PMID 26882989, 2016). "In the present study, using liver-specific TRAF3-KO/-transgenic mice, we identified hepatocyte TRAF3 as a positive regulator of HFD-induced or genetically induced insulin resistance, inflammatory responses and hepatic steatosis." (PMID 26882989, 2016). "The intraperitoneal glucose tolerance test and intraperitoneal insulin tolerance test demonstrated that HFD-induced insulin resistance in NTG mice was further exacerbated by TRAF3 overexpression in the liver." (PMID 26882989, 2016). "Importantly, in the present study, mice receiving the treatment of a specific TAK1 inhibitor significantly ameliorated insulin resistance, glucose intolerance, inflammatory response and hepatic fatty acid accumulation triggered by HFD in NTG and in TRAF3-LTG mice." (PMID 26882989, 2016).
mantle cell lymphoma (6 papers, 2013 to 2024). Mantle cell lymphoma is a rare form of malignant non-Hodgkin lymphoma affecting B lymphocytes in the lymph nodes in a region called the ``mantle zone''. "Because mutations in other NF-κB pathway genes, including BIRC3, TRAF2, TRAF3, MAP3K14 and CARD11, have been associated with ibrutinib resistance in mantle cell lymphoma, we next investigated whether mutations in NFKBIE could also affect the response to ibrutinib treatment." (PMID 38486128, 2024). "Human mature B cell lymphomas, including multiple myeloma (MM), mantle cell lymphomas (MCL) or marginal zone lymphomas (MZL), frequently harbor mutations or deletions of TRAF2, TRAF3 or BIRC3 (a.k.a. cIAP2)." (PMID 37679334, 2023).
osteoporosis (6 papers, 2018 to 2026). A condition of reduced bone mass, with decreased cortical thickness and a decrease in the number and size of the trabeculae of cancellous bone (but normal chemical composition), resulting in increased fracture incidence. "Consistent with this specific deletion of TRAF3 in myeloid progenitor cells in mice, results in mild osteoporosis associated with increased OC formation, further confirming that TRAF3 maintains bone homeostasis by inhibiting OC formation." (PMID 35011694, 2021). "Interestingly, TRAF3 protein levels are reduced in the bone from aged mice and humans, which directly links TRAF3 deficiency to age-associated osteoporosis." (PMID 35011694, 2021). "Traf3 MSC-specific knockout mice also developed early osteoporosis due to promoted osteoclast formation and reduced osteogenesis." (PMID 41158755, 2026). "Mice with TRAF3 deleted specifically in mesenchymal lineage cells (Prx1Cre;TRAF3fl/fl; called P-cKO) develop early onset osteoporosis by 9-m-old16." (PMID 36631487, 2023). "Nevertheless, elevation or stabilization of these inhibitory proteins, including TRAF3, p100, IRF8, and RBP-J, would be a novel strategy to treat a variety of bone diseases with bone loss, including osteoporosis and RA." (PMID 35011694, 2021). "We are currently investigating if prevention of TRAF3 degradation by long-term treatment of aging mice with CQ or IAP inhibitors can prevent age-related osteoporosis." (PMID 31243287, 2019). "These TRAF3 conditional knockout (cKO) mice develop early onset osteoporosis due to a combination of increased bone resorption and decreased bone formation." (PMID 31243287, 2019). "Mice with TRAF3 deleted in MPCs develop early onset osteoporosis due to reduced bone formation and enhanced bone destruction." (PMID 31243287, 2019). "They found that both lines of mice with conditional deletion of TRAF3 had normal skeletal development and phenotype, but they developed early onset osteoporosis due to increased osteoclast formation and activity." (PMID 30323820, 2018). "Inhibition of TRAF3 degradation by the autophagosomal inhibitor drug, chloroquine, inhibits osteoclast formation and prevents ovariectomy-induced osteoporosis in mice." (PMID 30323820, 2018). "Mice with TRAF3 conditionally deleted in mesenchymal cells also develop early onset osteoporosis due to a combination of increased osteoclast formation and reduced osteoblast formation." (PMID 30323820, 2018). "Mice genetically engineered to have TRAF3 deleted in osteoclast precursors and macrophages develop early onset osteoporosis, inflammation in multiple tissues, infections, and tumors, indicating that TRAF3 suppresses inflammation and tumors in myeloid cells." (PMID 30323820, 2018). "Mice with TRAF3 conditionally deleted in osteoclast precursor cells develop early-onset osteoporosis due to increased osteoclast formation." (PMID 30323820, 2018). "By degrading TRAF3 in MPCs, TGFβ1 promotes increased resorption and decreased bone formation, implicating it in the pathogenesis of low-level chronic inflammation-related osteoporosis." (PMID 36631487, 2023). "Nevertheless, prevention of TRAF3 degradation could be a novel strategy for the treatment of osteoporosis and RA." (PMID 35011694, 2021). "We conclude that pharmacologic stabilization of TRAF3 during aging could treat/prevent age-related osteoporosis by inhibiting bone destruction and promoting bone formation." (PMID 31243287, 2019). "Thus, low TRAF3 levels in older subjects most likely reflect the effects of age-related osteoporosis and not osteoarthritis." (PMID 31243287, 2019).
cervical carcinoma (5 papers, 2013 to 2024). A carcinoma arising from either the exocervical squamous epithelium or the endocervical glandular epithelium. "Promoter methylation status of cyclic GMP-AMP synthase (cGAS)/mitochondrial antiviral-signaling (MAVS)/tumor necrosis factor receptor-associated factor 3 (TRAF3) in control, cervical precancerous lesion (CPL), and cervical cancer (CC)." (PMID 31803230, 2019). "Association analysis of the promoter methylation level of cyclic GMP-AMP synthase (cGAS)/mitochondrial antiviral-signaling (MAVS)/tumor necrosis factor receptor-associated factor 3 (TRAF3) gene with the risk on cervical precancerous lesion (CPL), and cervical cancer (CC)." (PMID 31803230, 2019).
gastric cancer (5 papers, 2018 to 2021). A primary or metastatic malignant neoplasm involving the stomach. "Additionally, TRAF3 was identified to be a target mRNA of miR-455, miR-322, miR-17-92, and miR-188-3p in cerebral ischemic stroke, ischemia/reperfusion injury, and gastric cancer." (PMID 33817278, 2020).
glioblastoma (5 papers, 2018 to 2025). The most malignant astrocytic tumor (WHO grade IV). "al. demonstrate that TRAF3 loss promotes ECH1-mediated oxidation of polyunsaturated fatty acid (PUFA) and protects glioblastoma cells from lipid peroxidation damage." (PMID 39932808, 2025). "Overexpression of TRAF3 enhances the responsiveness of glioblastoma to ferropotosis and anti-PD-L1 immunotherapy." (PMID 39932808, 2025). "TRAF3, a key member of this family, is frequently suppressed in glioblastoma (GBM) due to promoter hypermethylation." (PMID 40919170, 2025). "Exogenous expression of TRAF3 enhanced the sensitivity of GBM to ferroptosis and effectively synergized with anti–programmed death–ligand 1 (anti–PD-L1) therapy in an orthotopic GBM model, indicating a promising therapeutic strategy for glioblastoma." (PMID 39932808, 2025). "Detailed examination indicated that the highest expressions of TRAF1, TRAF2, TRAF3, TRAF5, and TRAF7 were in Cholangiocarcinoma (CHOL), while TRAF4 was most expressed in Uterine Corpus Endometrial Carcinoma (UCEC) and TRAF6 in Glioblastoma multiforme (GBM)." (PMID 38825674, 2024).
glioma (5 papers, 2020 to 2025). A benign or malignant brain and spinal cord tumor that arises from glial cells (astrocytes, oligodendrocytes, ependymal cells). "While high expression of other members was associated with a poor prognosis, high-level TRAF3 correlated with significantly longer overall survival of patients with glioma." (PMID 39932808, 2025). "In the present study, we made an intriguing observation that TRAF3 was specifically associated with favorable survival outcomes in glioma cohorts compared with other types of tumors." (PMID 39932808, 2025). "To explore the functional implications of TRAF3 loss in glioma pathogenesis, we induced overexpression of TRAF3 in patient-derived GBM0709 cells and then profiled gene expression by transcriptome sequencing." (PMID 39932808, 2025). "Loss of TRAF3 by promoter hypermethylation correlates with a poor prognosis in glioma." (PMID 39932808, 2025). "To examine the cell-type–specific expression pattern of TRAF3 in glioma, we conducted single-cell RNA-Seq analysis based on publicly available datasets." (PMID 39932808, 2025). "Taken together, these results demonstrate that TRAF3 was repressed in high-grade glioma by promoter hypermethylation and that decreased TRAF3 level correlated with poor survival of patients with glioma." (PMID 39932808, 2025). "RIPK2 inhibits the proliferation and apoptosis of glioma cells by activating the NF-κB pathway and the mitogen-activated protein kinase (P38) pathway, and it inhibits tumour growth by regulating TRAF3 expression instead of the NF-κB pathway." (PMID 35473583, 2022). "The results demonstrated that among these factors, TRAF3 remained an independent predictor of a favorable prognosis in glioma, with elevated TRAF3 expression consistently correlating with improved survival outcomes, regardless of other clinical and genetic variables." (PMID 39932808, 2025). "This indicates that TRAF3 regulated glioma metabolism independently of the NF-κB pathway." (PMID 39932808, 2025). "Prior research has demonstrated that TRAF3 suppresses the alternative NF-κB pathways in glioma." (PMID 39932808, 2025). "Notably, despite the established role of TRAF3 as an inhibitor of the NF-κB pathway in glioma, restoration of the alternative NF-κB pathway by expression of MAP3K14 did not rescue the effect of TRAF3 overexpression on the oxidation capacity of GBM cells." (PMID 39932808, 2025). "In multiple glioma datasets including TCGA-glioma, the Chinese Glioma Genome Atlas (CGGA-glioma), and the Fine brain dataset, a decrease in TRAF3 levels was observed as the tumor grade advanced." (PMID 39932808, 2025). "In low-grade glioma (LGG), high TRAF3 expression was observed in tumor cells, while moderate expression was noted in myeloid cells." (PMID 39932808, 2025). "In glioma cells, RIP2 promotes cell growth by regulating TRAF3 and activating NF‐κB and p38 signaling pathways." (PMID 36184801, 2022). "This discrepancy suggests that TRAF3 expression in tumor cells, as opposed to nontumor cells, is the primary determinant of overall TRAF3 levels in glioma." (PMID 39932808, 2025). "Consistent with the mRNA data, TRAF3 protein levels were markedly diminished in glioma specimens relative to levels in nontumor tissues and negatively correlated with the glioma grade." (PMID 39932808, 2025).
non-Hodgkin lymphoma (5 papers, 2013 to 2023). Distinct from Hodgkin lymphoma both morphologically and biologically, non-Hodgkin lymphoma (NHL) is characterized by the absence of Reed-Sternberg cells, can occur at any age, and usually presents as a localized or generalized lymphadenopathy associated with fever and weight loss. "This is corroborated by frequent TRAF3 mutations detected in canine non-Hodgkin lymphomas (NHL)." (PMID 36776285, 2023). "For example, not only Traf3 deficiency leads to B lymphoma development in mice, transgenic overexpression of TRAF3 in B cells also promotes B cell differentiation and mature non-Hodgkin lymphomas in mice." (PMID 34745083, 2021).
splenic marginal zone lymphoma (5 papers, 2015 to 2023). Splenic marginal zone lymphoma is a rare, indolent B-cell non-Hodgkin lymphoma characterized by abnormal clonal proliferation of mature B-lymphocytes with involvement in the spleen, bone marrow and, frequently, the blood. "We previously reported that Traf3 deficiency results in prolonged survival of mature B lymphocytes, which eventually leads to spontaneous development of splenic marginal zone lymphoma and B1 lymphoma in B-Traf3-/- mice." (PMID 34745083, 2021).
acute pancreatitis (4 papers, 2020 to 2023). An acute inflammatory process that leads to necrosis of the pancreatic parenchyma. "Another work implicates miR-339-3p in inhibiting caerulin-induced acute pancreatitis by targeting TRAF3, which promotes inflammation in pancreatitis cells." (PMID 36982154, 2023). "In acute pancreatitis, overexpression of RAB21 promotes the caerulein-induced MKK3 (mitogen-activated protein kinase kinase 3)-TRAF3 (TNF receptor-associated factor 3) association." (PMID 35163051, 2022).
atherosclerosis (4 papers, 2022 to 2026). A disease characterized by the build-up of fatty material and calcium deposition in the arterial wall resulting in partial or complete occlusion of the arterial lumen. "Due to the limited viability of TRAF3−/− mice, an in vivo atherosclerosis study is missing." (PMID 35252400, 2022). "The TRAF3 gene, an immunity-related gene in cattle, was previously found to be a negative regulator of the nuclear factor-κB (NF-κB) pathway, a pathway known to increase cholesterol accumulation within the cell to promote atherosclerosis and macrophage foam cell formation in recent culture studies." (PMID 38674374, 2024). "In another study, the lack of the TRAF2, TRAF3, and TRAF5 binding site on CD40 in MHCII+ cells did not interfere with neointima formation after arterial injury and atherosclerosis." (PMID 35252400, 2022).
colorectal cancer (4 papers, 2014 to 2025). A primary or metastatic malignant neoplasm that affects the colon or rectum. "We identified mutated in colorectal cancer (MCC) as a gene strikingly up-regulated in TRAF3-deficient mouse B lymphomas and human MM cell lines." (PMID 25200342, 2014). "TRAF3 also plays pro-apoptotic roles in human bladder and colorectal carcinoma cells upon CD40 ligation via BAX/BAK-caspase 9- and ROS- dependent mechanisms." (PMID 34745083, 2021). "Hypoxic colorectal cancer‐derived extracellular vesicles deliver microRNA‐361‐3p to facilitate cell proliferation by targeting TRAF3 via the noncanonical NF‐κB pathways." (PMID 33784010, 2021).